HIF1A (hypoxia inducible factor 1 subunit alpha)
Diseases named in the same sentence as HIF1A in open-access papers (continued):
Sharing a sentence is not in itself a finding about the gene and the disease.
disc degeneration (11 papers, 2018 to 2026). "The HIF-1α/Notch signaling pathway regulates cell proliferation, apoptosis, and metabolism in the intervertebral discs (IVDs) and is implicated in disc degeneration." (PMID 32723315, 2020). "Further research evaluating the long-term effects and clinical translation of quercetin or other HIF1A modulators could potentially lead to efficacious, disease-modifying treatments for the debilitating chronic low back pain caused by disc degeneration." (PMID 39296087, 2024). "Notably, inhibition of Hif1α signaling activity using either a selective Hif1α inhibitor (2ME2) or conditional deletion of Hif1α in Vhl-deficient mice with DDD alleviated the pathological changes of disc degeneration." (PMID 34983922, 2022). "Studies have shown that the HIF‐1α signaling pathway is downregulated in degenerated discs, indicating that heightened oxygen tension suppresses HIF‐1α expression in NP cells and contributes to disc degeneration." (PMID 40231808, 2025). "While the results identify HIF1A as a potential therapeutic target of quercetin in alleviating compression-induced cell death and disc degeneration, there are some important limitations to consider." (PMID 39296087, 2024). "Targeting the HIF1A pathway represents a promising therapeutic strategy for degenerative disc diseases." (PMID 39296087, 2024). "The hypoxia inducible factor 1 subunit alpha (HIF1A), one of the key FRDEGs identified in this study, was reported to be decreased with the disc degeneration and participated in the IDD process through interacting with autophagy." (PMID 36814575, 2023). "Our findings uncovered a vital protective role of CD24-positive NP cells against disc degeneration and revealed that HIF-1α-NOTCH1 pathway activation is essential for the maintenance of CD24-positive notochordal cells." (PMID 30598696, 2018). "HIF-1α and Notch-related components are potential biomarkers and the HIF-1α/Notch signaling pathway may serve as a promising therapeutic target for disc degeneration in patients with MCs." (PMID 32723315, 2020). "Moreover, OCN knockdown was proceeded to investigate whether LEP regulated glycolysis through OCN‐mediated HIF‐1α in vitro in disc degeneration." (PMID 41474013, 2026). "Therefore, HIF-1α and ER may serve as key points to improve the efficacy of ADSCs in treating disc degeneration." (PMID 37158945, 2023). "Therefore, the HIF-1α/Notch signaling pathway plays an important role in disc degeneration, and may serve as a potential therapeutic target for the restoration of cell numbers in degenerative disc disease." (PMID 32723315, 2020). "Furthermore, we explored the relationship between MCs and disc degeneration using imaging, biochemical, and immunohistochemical methods to determine whether the expression of HIF-1α and Notch may aid the diagnosis and treatment of degenerative disc diseases." (PMID 32723315, 2020). "We have shown that there is an interaction between BMAL1 and RORα and they modulate HIF-1α activity as well as ECM homeostasis and perturbation in circadian clock genes results in disc degeneration." (PMID 38510179, 2024). "Recently, biological studies on the prevention of early disc degeneration by promoting ECM synthesis, including NP cells, by upregulating HIF-1α have been reported." (PMID 34067899, 2021). "Western blotting showed that the expression of HIF-1α and NDUFA4L2 was decreased as the degree of disc degeneration increased." (PMID 31740659, 2019). "In conclusion, this study has demonstrated that disc degeneration is correlated with elevated LEP expression, and the mechanism of LEP promoting calcification and ossification is related to the glycolysis process induced by HIF‐1α." (PMID 41474013, 2026). "Targeting the HIF1A pathway through natural compounds like quercetin could represent a promising strategy for the clinical management of LDD and potentially other degenerative disc diseases." (PMID 39296087, 2024).
disc degeneration (continued). "Moreover HIF1A has exerted critical regulatory functions in the disc degeneration process, and it could be also an important target to prevent the IDD development." (PMID 36814575, 2023).
hemangioblastoma (11 papers, 2004 to 2025). "In the context of VHL-deficient hemangioblastomas, the stabilization of both HIF-1α and HIF-2α has been suggested to drive the tumor’s highly vascularized environment, thereby promoting its growth and survival." (PMID 40427061, 2025). "Nevertheless, in all patient-derived HB cell cultures, the levels of HIF-1α and HIF-2α expression were significantly higher than in non-hemangioblastoma cells, with a slightly higher proportion of cells showing positivity for HIF-1α compared to HIF-2α." (PMID 40427061, 2025). "Given the limited efficacy of selective HIF-2α inhibition in CNS hemangioblastomas, our study explores a broader therapeutic approach by targeting both HIF-1α and HIF-2α simultaneously." (PMID 40427061, 2025). "In hemangioblastoma, HIF1A expression is found in most cell samples from the well-vascularized tumor." (PMID 35252204, 2022). "Hemangioblastoma pathogenesis is believed to be secondary to dysregulation of the HIF pathway with inappropriate elevation of HIF-1a leading to increased expression of erythropoietin and vascular endothelial growth factor." (PMID 28388566, 2017). "This fact was also tested in hemangioblastoma cells that were functionally hypoxic, as shown by the expression of HIF1α and HIF2α under normal culture conditions." (PMID 26394686, 2015). "The involvement of both HIF-1α and HIF-2α in tumor growth and vascularization may explain why selective HIF-2α inhibitors like Belzutifan show limited efficacy in VHL-deficient hemangioblastomas." (PMID 40427061, 2025). "Moreover, ICI-118,551 also impaired the nuclear internalization of HIF-1α in Hemangioblastomas and hypoxic primary endothelial cells, reducing significantly the activation of HIF-target genes and halting the tumour-related angiogenic processes." (PMID 31296894, 2019). "Biallelic VHL inactivation in hemangioblastoma results in insufficient degradation of HIF-1α, which then results in the inappropriate transcription of effectors normally expressed in hypoxic states, such as vascular endothelial growth factor (VEGF) or platelet derived growth factor B (PDGF B)." (PMID 25589003, 2014). "Hence, together these results suggest that dual inhibition of HIF-1α and HIF-2α could be a promising non-invasive strategy for the treatment of VHL-associated hemangioblastomas or as a complementary therapy to surgery." (PMID 40427061, 2025). "This study aims to analyze the growth profile, as well as HIF-1α and HIF-2α mRNA and protein levels, in an in vitro CNS hemangioblastoma model based on patient-derived primary cell cultures." (PMID 40427061, 2025). "The percentage of cells positive for HIF-1α and HIF-2α varied among the different primary hemangioblastoma cells, indicating some heterogeneity in hypoxia-related protein expression." (PMID 40427061, 2025). "HIF1α and HIF2α play crucial roles in VHL disease, particularly with respect to ccRCC and hemangioblastoma." (PMID 35505422, 2022). "A review of various immunohistochemical studies demonstrated that HIF1α protein is detectable in approximately 70% of ccRCCs, which are consistent with our IHC staining results of RCC and hemangioblastoma tissues." (PMID 35505422, 2022). "Despite of the controversy, HIF1α and HIF2α have been identified to be essential for VHL disease, particularly for ccRCC and hemangioblastoma." (PMID 35505422, 2022). "Notably, VEGF and EPO are HIF-1α targets involved in angiogenesis and oxygen supply to cells, while SOX2 is a transcriptional target of HIF-2α and is a stemness target implicated in the undifferentiated nature of the mesenchymal component predominant in hemangioblastomas." (PMID 26394686, 2015). "Expression of galectin-3 was correlated with the expression of HIF-1α and VEGF in the development of hemangioblastoma." (PMID 26222311, 2015).
hemangioblastoma (continued). "VEGF, one of the main targets of HIF-1α, and a potent mediator of both angiogenesis and vasculogenesis, was also measured in the supernatants of two different hemangioblastoma samples cultured with and without propranolol." (PMID 26394686, 2015).
Infertility (11 papers, 2017 to 2026). "Vascular abnormalities caused by HIF-1α further contribute to infertility by impairing ovarian blood flow." (PMID 40136686, 2025). "Hypoxia triggers a molecular response of adaptation through the HIF-1α and NFκB activation, inducing hypoxic cell damage, an inflammatory state which can be cause of infertility." (PMID 38455658, 2024). "VEGFA, a downstream target of HIF-1α, associated with infertility in mice, exhibited increased expression in the seminiferous tubules of FD patients, consistent with our immunofluorescence and RT-PCR results." (PMID 38455658, 2024). "They reported increased β-glucuronidase activity, enhanced ERβ activity, and elevated levels of IL-1β and HIF-1α in infertile women with dysbiosis (defined as Lactobacillus spp < 90% in endometrial samples)." (PMID 41413507, 2025). "have discovered that the environmental pollutant di-2-ethylhexyl phthalate can induce ferroptosis in mouse testes and lead to infertility through the mediation of the HIF-1α/HO-1 signaling pathway." (PMID 37876811, 2023). "Uterine-specific Hif-1α and Hif-2α knockout mice show subfertility and infertility, respectively." (PMID 38790978, 2024). "The alteration of HIF-1α/NFκB axis, in turn, may damage the proper organization and function of the seminiferous cells leading to infertility." (PMID 38455658, 2024). "However, we detected differences in this expression in the healthy vs. infertile group: HIF1A, VEGFR-2 and VEGFR-3 expression was at the higher level in the healthy volunteers group." (PMID 34202508, 2021). "Defining the distinct roles of HIF-1α and HIF-2α supports the development of therapies targeting hypoxia-responsive pathways in infertility and obstetric disease." (PMID 41684012, 2026). "We previously demonstrated phosphorylation of STAT3 in eutopic endometrium of infertile women with this disorder leading to over-expression of the oncogene BCL6 and stabilization of hypoxia-induced factor 1 alpha (HIF-1α)." (PMID 28754906, 2017). "Here, we report that endometrial upregulation of HIF1α, VEGFA, and VEGFR2, as well as excessive vascularization in the peri-implantation endometrium, may reduce endometrial receptivity in infertile CE patients." (PMID 36531509, 2022).
knee osteoarthritis (11 papers, 2015 to 2026). "It is worthy of note that HIF-1α is closely associated with disease severity in knee osteoarthritis." (PMID 34465337, 2021).
osteonecrosis (11 papers, 2013 to 2026). A none disease characterized by death of bone tissue due to a lack of blood supply. "In the present study we have investigated the correlation of C1772T, G1790A and C111A HIF-1α polymorphisms, with the appearance of osteonecrosis in a Greek population." (PMID 24260273, 2013). "However, in the hypoxic environment associated with glucocorticoid-induced osteonecrosis, PHDs are inhibited due to decreased oxygen concentration, impeding the ubiquitination of HIF-1α and resulting in its accumulation in the cell nucleus." (PMID 40319297, 2025). "The aim of our study was to test whether EDHB, a small-molecule prolyl hydroxylase inhibitor (PHI) which inhibits the degradation of HIF-1α, prevents the steroid-associated osteonecrosis of the femoral head." (PMID 25244080, 2014). "Therefore, based on this scientific background, we speculate that the oxidative damage associated with glucocorticoid-induced osteonecrosis may be related to the ROS/PHD2/HIF-1α signaling pathway, and intervention in this signaling pathway may help to delay the progression of osteonecrosis." (PMID 40319297, 2025). "Hypoxic preconditioning of MSCs increases HIF-1α in Exo and promotes bone regeneration in a rabbit model of osteonecrosis." (PMID 39684778, 2024). "Nevertheless, pretreatment with an HIF-1α inhibitor significantly disrupted the protective effects of DMOG on MPS-induced osteonecrosis in rabbits." (PMID 37189610, 2023). "In summary, HIF-1α pathway activation is required to partially alleviate MPS-induced osteonecrosis through its potential for angiogenesis and bone remodeling in vivo." (PMID 37189610, 2023). "In summary, this study demonstrates that HIF-1α transgenic BMCs possess better capabilities of osteogenesis and angiogenesis in vitro, and can increase vascularization and bone regeneration in the early-stage osteonecrosis of femoral head in the rabbit model." (PMID 23675495, 2013). "Concerning osteonecrosis, little is really known about HIF-1α SNPs." (PMID 24260273, 2013). "The overexpression of pro-regenerative proteins in MSCs has also been explored, with HIF-1α-overexpressing EVs from bone marrow MSCs enhancing both osteogenesis and angiogenesis, and improving bone regeneration in a rabbit glucocorticoid-induced osteonecrosis model." (PMID 41410757, 2025). "However, it is unclear whether YGY decoction exerts protective effects against oxidative damage in glucocorticoid-induced osteonecrosis through the ROS/PHD2/HIF-1α signaling pathway." (PMID 40319297, 2025). "It is possible that, despite HIF-1α upregulation, HIF-1α expression is relatively low at the late phase of osteonecrosis." (PMID 37189610, 2023). "Taken together, these results show that directional migration of EPCs can be partially activated through HIF-1α activation after DMOG treatment, thereby facilitating the prevention of the progression of steroid-induced osteonecrosis of the femoral head." (PMID 37189610, 2023). "Eight weeks after the induction of osteonecrosis, Alendronate combined with the DFO group demonstrated higher expression of osteocalcin and VEGF and upregulated signal factors of HIF-1α and β-catenin, and decreased level of RANKL." (PMID 37670365, 2023). "Ethyl 3,4-dihydroxybenzoate (EDHB) is a small molecule antioxidant, which inhibits PHD activity, stabilizes HIF-1α, and promotes angiogenesis by upregulating VEGF, thus preventing steroid-induced osteonecrosis of the femoral head." (PMID 36428981, 2022). "Since hypoxia is a key feature of ON, we might expect that downstream effectors of HIF-1α, like VEGF or other angiogenic or metabolic agents could be of value in the diagnosis, progression and therapy of bone diseases like osteonecrosis." (PMID 24260273, 2013).
paraganglioma (11 papers, 2009 to 2025). A benign or malignant neoplasm arising from paraganglia located along the sympathetic or parasympathetic nerves. "Similarly, elevated HIF1α activity has only been demonstrated in a study of paragangliomas carrying a VHL mutation." (PMID 28187001, 2017). "RET and VHL are HSP90 clients, and it has been reported that the expression of HIF-1α and HIF-2α (an HSP90 client) were implicated in the pathogenesis of paraganglioma with SDHB and SDHD mutations." (PMID 35932386, 2022). "Additionally, an antisense transcript to HIF-1α has been shown to be capable of inhibiting HIF-1α during chronic hypoxia, and also being a marker for metastasis free survival in paragangliomas." (PMID 25101115, 2014). "Paraganglioma with high levels of HIF2α do not accumulate HIF1α, and vice versa, suggesting that the two subunits undergo distinct deregulatory pathways." (PMID 35740651, 2022).
Peritoneal Fibrosis (11 papers, 2015 to 2024). Disorder characterized by a wide range of structural changes in PERITONEUM, resulting from fibrogenic or inflammatory processes. "Furthermore, the expression of STAT3/HIF-1α signaling might underlay the EMT process of mesothelial cells so as to cause peritoneal fibrosis, while STAT3 blockade might be an effective therapy for PF in long-term PD patients." (PMID 34193173, 2021). "In summary, we demonstrated that Canagliflozin prevents peritoneal fibrosis induced by high glucose and improves peritoneal function by alleviating peritoneal hypoxia and inhibiting HIF-1α and TGF-β/p-Smad3 signaling pathways." (PMID 37251320, 2023). "The participation of hypoxia and HIF-1α in the development of peritoneal fibrosis has been previously demonstrated." (PMID 37251320, 2023). "A recent report showed that STAT3/HIF-1α signaling participates in peritoneal fibrosis during long-term peritoneal dialysis (PD) treatment." (PMID 34944635, 2021). "Taken together, these findings identified a novel mechanism linking STAT3/HIF-1α signaling to peritoneal fibrosis during long-term PD treatment." (PMID 34193173, 2021). "Administration of S3I-201 prevented the progression of peritoneal fibrosis, angiogenesis, macrophage infiltration as well as the expression of HIF-1α in the peritoneal membrane induced by high glucose." (PMID 34193173, 2021). "LMWH ameliorates peritoneal function and inhibits peritoneal fibrosis, possibly through suppression of HIF-1α, VEGF and TGF-β1." (PMID 25723475, 2015). "In PD mice models, the upregulation of nestin proteins could stimulate peritoneal fibrosis by protecting HIF1-α from proteasomal degradation." (PMID 36101746, 2022). "We have certified that the HG/STAT3/HIF-1α signaling pathway might play an important role in the pathogenesis of peritoneal fibrosis induced by high-glucose based dialysis fluid." (PMID 34193173, 2021). "In conclusion, our study demonstrated that IP administration of LMWH could improve peritoneal function and relieve peritoneal fibrosis, possibly through suppression of HIF-1α, VEGF and TGF-β1." (PMID 25723475, 2015). "Our previous clinical trials had confirmed that LMWH could protect peritoneal structure and function, and that HIF-1α was up-regulated in CAPD patients depending on the extent of peritoneal fibrosis." (PMID 25723475, 2015). "Additionally, blocking the hypoxic response or HIF-1α inhibition could mitigate peritoneal fibrosis." (PMID 37251320, 2023). "In conclusion, we showed that Canagliflozin could improve peritoneal fibrosis and function by ameliorating peritoneal hypoxia and inhibiting the HIF-1α/TGF-β/p-Smad3 signaling pathway, providing theoretical support for the clinical use of SGLT2 inhibitors in patients on peritoneal dialysis." (PMID 37251320, 2023). "This study provided the first evidence that pharmacological inhibition of STAT3 prevented peritoneal fibrosis through the HG/STAT3/HIF-1α signaling pathway, indicating STAT3 inhibitor might be an effective therapeutic strategy for PF in PD patients undergoing long-term treatment." (PMID 34193173, 2021). "This analysis identified hub genes, signaling pathways, and key transcription factors involved in peritoneal fibrosis and highlighted the novel glucose-dependent regulation of TGF-β1 by HIF-1α." (PMID 38443979, 2024). "At the same time, Canagliflozin significantly inhibited the HIF-1α/TGF-β/p-Smad3 signaling, prevented peritoneal fibrosis and peritoneal thickening, and improved peritoneal transportation and ultrafiltration." (PMID 37251320, 2023). "We demonstrated that HDAC8 promoted the EMT of HPMCs via EGFR/ERK1/2/STAT3/HIF-1α, induced M2 macrophage polarization via STAT6 and PI3K/Akt signaling pathways, and ultimately accelerated the process of peritoneal fibrosis." (PMID 36911746, 2023).